CD4 (CD4 molecule)
Diseases named in the same sentence as CD4 in open-access papers (continued):
Sharing a sentence is not in itself a finding about the gene and the disease.
tumor (continued). "High levels of CD4+ and CD8+ T cells in all groups vaccinated with RtH-GD3P4 or HaH-GD3P4, compared to controls, are a potency factor for effective anti-tumor immune response." (PMID 35736195, 2022). "Preclinical studies show that CD4+ T cells mediate the crosstalk between CAR-T cells and the endogenous immune system, which is necessary for optimal CAR-T-cell efficacy to prevent tumor escape and improve long-term survival outcomes." (PMID 35874660, 2022). "GzmB expression was also detected in higher percentages of CD4 and CD8 tumor infiltrating lymphocytes (TILs) in vaccinated mice." (PMID 36569934, 2022). "Regulatory T cells (Treg), a sub-population of CD4+ T cells capable of downregulating anti-tumor immune responses, are induced by MDSC in the periphery and are attracted to the tumor site by secretion of the chemokines CCL4 and CCL5." (PMID 35455309, 2022). "Both tumor-promoting immune cells such as macrophages M2, and antitumor immune cells for example CD8 T cells and CD4 memory activated cells were also discovered enrich in ferroptosis cluster-A." (PMID 35155577, 2022). "Macrophages secrete TGF-β and IL-10 to convert Th1 cells into Th2 cells, thus reversing the anti-tumour effects of CD8+ cytotoxic T cells and CD4+Th1 cells." (PMID 35591854, 2022). "It is known that Tregs are suppressors of antitumor responses that disrupt the maturation of dendritic cells (DC) and prevent the activation of CD4+ effector and CD8+ cytotoxic cells in the tumor microenvironment." (PMID 35154165, 2022). "Both DCs and CD4+ T cells were proven related to Bacillus Calmette Guerin (BCG)-induced immune response, which indicated the importance of tumor-infiltrating immune cells in BLCA progression and therapy." (PMID 35154117, 2022). "Recipients of VIP-R antagonist peptide/anti-PD-1 combination therapy had increased homing, activation and proliferation of intra-tumoral CD4+ and CD8+ T cells and marked increases in tumor-antigen-specific T cells within the TME." (PMID 36302761, 2022). "Data from a syngeneic tumor model with CD4+ T cell-specific ablation of S1PR1 indicate that S1PR1 on CD4+ T cells regulates intratumoral Treg expansion leading to CD8+ T cell suppression and tumor progression through STAT3-dependent activation of Tregs." (PMID 35163211, 2022). "TAMs, CD4+ T cells, CD25+ T cells, Tregs, and MDSCs are other tumor-infiltrating immunosuppressive cells that dominate in the TME and sustain tumor progression." (PMID 36298472, 2022). "According to the results of the H&E staining of tumor tissues and the immunohistochemical staining of CD4 and CD8 cells in tumor tissues, the tissues were divided into two groups: the low-immune infiltration group and the high-immune infiltration group." (PMID 35186082, 2022). "Compared with the control group, the expression of CD4 and CD8 in HCC mice indicated that the local natural immunity of the tumor was activated, whereas the increased PD-1 and CTLA-4 expression indicated the occurrence of immune-suppression." (PMID 35178106, 2022). "We observed a baseline tumor immune infiltrate in most of the patients, which increased after NAT, both for CD4+ and CD8+ T cells and for B cells." (PMID 35562400, 2022). "In this study, flow cytometry-based characterization shows that CD4+ and CD8+ T cells become activated in situ once they exit the circulation and enter the tumor-bearing lungs." (PMID 36733396, 2022). "Concurrently, the TIMER database showed that the expression of BAIAP2L2 in LIHC was positively correlated with tumor infiltrating cells, including B cells, DCs, CD8+ T cells, CD4+ T cells and macrophages." (PMID 36338652, 2022). "TILS can be subdivided into: CD4+ antigen-presenting T-helpers (Th) CD4+ immunosuppressive T-regs, and cytotoxic CD8+ T-cells – involved in direct tumor cell killing." (PMID 36505861, 2022). "This clearly showed that AKT activation induces IFN-γ expression on CD4 and CD8 T-cells in a manner correlated with tumor rejection." (PMID 36323740, 2022).
tumor (continued). "Since CD4+ Th2 cells and Th2 cytokines such as interleukin-4 (IL-4), IL-5, IL-6, IL10 and IL13 were thought to be associated with immunosuppressive contexture and tumor-promoting effects, we believed that LMNB1 could be considered as a biomarker of immunosuppressive microenvironment." (PMID 35241075, 2022). "Agonists targeting OX40 can provide powerful co-stimulatory signals, thereby enhancing the expansion and proliferation of CD4 + and CD8 + T cells that recognize tumor antigens." (PMID 35000592, 2022). "The anti-tumor activity of AN3025 was dependent on the existence of CD4+ and CD8+ T cells, as depletion of CD4+ and CD8+ T cells abolished the anti-tumor activity of AN3025." (PMID 35251028, 2022). "This study also showed that significant differences between the PD-1 expression and the occurrence of metastases to distant organs (M) concerned the CD8+ T cells in the blood samples as well as the CD4+ and CD8+ T cells in the tumor and lymph node samples." (PMID 35158748, 2022). "In particular, the proportion of CD45+, CD3+ T, CD8+ T cells in tumor tissue and the proportion of CD3+ T, CD8+ T, CD4+ T cells in peripheral blood were significantly increased." (PMID 36518768, 2022). "We next investigate the TCR content in sorted CD4+CD39+PD1+ and CD8+CD39+PD1+ TILs, and show that these subsets are prominently enriched for TCR clusters, a substantial fraction of which consists of tumor-specific TCRs." (PMID 35377314, 2022). "For example, neutrophils, macrophages and CD4 + regulatory T cells support tumour development, whereas CD8 + cytotoxic T cells, natural killer cells and gamma-delta T cells actively eliminate tumours." (PMID 35904677, 2022). "Previous studies suggested that cancer cells also acquired immune regulatory membrane proteins such as PD-L1, CD4, CD45, CTLA4 and Tim3 expressed in lymphocytes, which in turn contribute to the development of the immunosuppressive tumor microenvironment." (PMID 35794622, 2022). "The cell numbers of lymphocyte subsets, including CD4+, CD8+, CD3+, and CD56 + T cells, are decreased in patients with advanced cancer, leading to weakened lymphocyte-mediated anti-tumor immune responses." (PMID 35570842, 2022). "It was observed in tumor center that the tumor tissue presented a high TMEM170B expression level, the infiltration Levels of CD4+T Cells, CD8+T cells was relatively active." (PMID 35601487, 2022). "After balancing the impact of tumor purity, the mRNA levels of the DTL gene strongly correlated with most markers of activated CD8+ and CD4+ T cells in HCC." (PMID 35392073, 2022). "UDP was reported to trigger anti-tumor activity by favoring TH1 and TH17 response over TH2 response and stimulating CD4+/CD8+ effector T-cell proliferation." (PMID 36430925, 2022). "Massive infiltration of CD3+, CD4+, and CD8+ cells was observed in Smad4KO tumor tissues by IHC staining." (PMID 35064757, 2022). "Immunohistochemical staining of the tumor tissue of one 51-year-old female LUAD patient showed some degree of protein expression of both CCL17 and CD3G (CD4/CD8+ T cell marker molecule)." (PMID 35321241, 2022). "A small proportion (<1% CD8 and 2% CD4) of TCR clonotypes observed ex vivo were evident in both expanded cultures and tumor." (PMID 35361728, 2022). "The TIMER2 database results revealed that in most tumours, FAM46C was positively correlated with CD4+ and CD8+ T-cell infiltration levels and negatively correlated with CD4+ Th1-cell infiltration levels (p < 0.05)." (PMID 35222533, 2022). "Treatment with the TLR7 agonist imiquimod promotes the infiltration of CD4+ and CD8+ T cells, decreases the absolute number of Tregs in the tumor microenvironment and establishes anti-tumor immune memory in mice." (PMID 35680568, 2022). "TIMER dataset indicated that CCNA2 expression was negatively correlated with tumor purity, thus enhancing infiltration of several immune cell types in ccRCC, including B cell, CD8+ T cell, CD4+ T cell, macrophage, neutrophil, and dendritic cell." (PMID 35401923, 2022).
tumor (continued). "The infiltration of immune cells, including the CD4+ and CD8+ T cells, was significantly increased as evidenced by the immunofluorescence staining of the tumor sections." (PMID 35988145, 2022). "DCs can present antigens to T and B cells and sensitize CD4+ and CD8+ lymphocytes to secrete cytokines including interferon γ to inhibit and destroy tumor tissues." (PMID 35903696, 2022). "The CD4+ and CD8+ T cells have important anti-tumour immune functions, thus combined anaesthesia had a negative influence on cellular immunity." (PMID 35982423, 2022). "Even distantly in the inguinal lymph node, the DLN of the flank tumor, we observed a decrease in T cell priming via LFA-1+CD44+CD4 T cells in mice treated with ENI." (PMID 36385142, 2022). "Using a linear correlation approach between immunotype and the SGR for each tumor, we observed tumor growth inhibition was most strongly correlated with higher levels of HLA-DR+TIM-3-TNFα+ and TNFα+IFNγ+ CD4+ T cells." (PMID 36419897, 2022). "Given the immunogenic nature of MOC1 and consistent with previous literature, there were substantially more CD4+ and CD8+ T lymphocytes present in MOC1 tumor tissue when qualitatively compared to MOC2 tumor tissue." (PMID 36172037, 2022). "Second, the low infiltration of CD4+ T lymphocytes and CD8+ T lymphocytes in the tumor microenvironment has been found to predict poorer survival in various malignancies." (PMID 35662746, 2022). "Th17 cells differentiate from Naïve CD4+ T cells induced by both TGF-β and IL-6, and they affect inflammation and progression of tumor diseases." (PMID 35402261, 2022). "In our study, there was a positive correlation between HDAC1 expression levels and tumor purity, and CD8+ T cells', CD4+ T cells', neutrophils', and dendritic cells' infilitration levels." (PMID 35845599, 2022). "At the same time, resveratrol and curcumin can also reduce the expression levels of CD28 and CD80 in CD4+ T cells, up-regulate the expression of CTLA-4, and regulate tumor growth." (PMID 36505462, 2022). "The CD3+ inflammatory marker and two subsets of T cells, namely, CD4+ T helper cells and CD8+ cytotoxic T lymphocytes were quantified and their localization was assessed in extracted tumors at different times after tumor grafting." (PMID 35327351, 2022). "Simultaneously, the TIMER database showed that the expression of BAIAP2L2 in LIHC was positively correlated with tumor infiltrating cells, including B cells, CD8+ T cells, CD4+ T cells, macrophages, neutrophils and dendritic cells." (PMID 36338652, 2022). "Our results identified a correlation of RELL2 with MDSCs, CD4+ T cells, and CD8+ T cells and the correlation of RELL2 with tumor immune infiltration." (PMID 35634441, 2022). "Immunosuppressive Th17 and Treg cells were among the most increased CD4+ T cells while naive CD8+ T cells were reduced in tumors, likely reflecting the activation and expansion of T cells in the tumor." (PMID 36550535, 2022). "Through human leukocyte antigen molecules, these antigens are presented to (CD4+ or CD8+) T-cells and activate the well-known cascade of tumor-cell recognition, activation, and expansion of effector cells that will induce a tumor-specific immune response." (PMID 35326709, 2022). "Maximum expression of CD4+ and CD8+ (green and red fluorescence, respectively) in the tumor section of anti‐PD‐L1‐DOX‐R848‐MIP‐3α/TKNP‐treated mice compared to that in other groups suggested maximum intratumoral infiltration of immune cell." (PMID 37693071, 2022). "CD3, CD4 and CD8 IHC staining was performed in tumor tissues collected at different time points after treatment." (PMID 35890355, 2022). "Within the present study, a significant decrease in CD3+CD4+CD69+ cells was observed at week six, potentially due to the removal of the immunosuppressive tumour." (PMID 35154142, 2022).
tumor (continued). "After 24 h of incubation with DuoBody-CD3x5T4, memory CD4+ and CD8+ T-cell subsets killed MDA-MB-468 tumor cells more efficiently than their naive counterparts." (PMID 36271507, 2022). "Importantly, DOCK8 deficiency affects the survival of immune cells such as T cells and NKT cells in cancer which might be through cytoskeleton reconstruction, CD4+ T cell differentiation, immune synaptic formation, tumor immune infiltration and tumor immune surveillance." (PMID 36386145, 2022). "Analysis of tumour-immune cell infiltration using the tumour immune estimation resource (TIMER) and the CIBERSORT function showed a positive correlation between AHNAK2 expression and B-cell, CD4+ T cell, macrophage, neutrophil, and dendritic cell infiltration." (PMID 35158796, 2022). "For instance, CD4+ T cells, CD8+ T cells, and Treg cells play important roles in tumor recurrence, metastasis, and immunotherapy response." (PMID 35355983, 2022). "On the 14th day after PDT treatment, various immune signal molecules were detected in tumor and lymphoid tissues, including IFN-γ, TNF-α, and CD4+T cells, CD8+ T cells, and DCs." (PMID 35832074, 2022). "So far, there are few reports about activated memory CD4+T cells infiltration and related genes in the DLBCL tumor microenvironment." (PMID 35711924, 2022). "MIF has additionally been shown to inhibit the activation of CD4+, CD8+ T cells and CTLs in the tumor regions of cancer-bearing mice." (PMID 35842634, 2022). "Currently, CD4+ T cells and MHC class II molecule restricted antigenic peptides have received increasing attention in tumour immunity." (PMID 36016159, 2022). "Despite an initial rise at 14 days post-tumor implantation, cytotoxic (CD3+CD8+), helper (CD3+CD4+), and Treg (CD3+CD4+FOXP3+) T-cell populations decreased by day 28 with a concordant increase in the percentage of granulocytic MDSC populations." (PMID 35626103, 2022). "Postoperative CD3+ lymphocytes, CD4+ lymphocytes and CD4+ /CD8+ lymphocyte ratio presented bi‐phasic changes, which indicated an initial decrease and a subsequent increase after neurosurgical tumor resection." (PMID 36169250, 2022). "After tumor induction, the mice receiving an FMT from responders had a better response to the PD-1 blockade and showed an increased expression of CXCR3+ CD4+ T cells in TME." (PMID 36230554, 2022). "Specifically, in sensory neuron-overactivated melanoma mice, the number of MDSCs and neutrophils significantly decreased, while tumor-infiltrating DCs, CD8 + T cells, CD4 + T cells, γδ T cells and NK cell was detected to increase." (PMID 36072337, 2022). "CD4+ and CD8+ PC T-cells expressed significantly higher levels of IFN-γ compared with primary tumor T-cells (p = 0.039 and p = 0.0235)." (PMID 35844581, 2022). "NECTIN1 and NECTIN4 are most strongly expressed in tumor cells, but NECTIN2 and NECTIN3 are also expressed in some lymphocyte cell types, while TIGIT is largely expressed in Tregs and exhausted CD4+ T cells." (PMID 35995947, 2022). "Further, in a Lewis lung carcinoma model, IRE + STING increased the tumor infiltration of CD8+ and CD4+ T cells and induced a shift in the M1/M2 macrophage ratio towards the anti-tumor M1 phenotype." (PMID 35740542, 2022). "High DC infiltration polarizes CD4+ and CD8+ tumor-infiltrating lymphocytes, while relatively poor DC abundance and antigen-presenting function impair the T cell response, leading to tumor immune escape." (PMID 36726981, 2022). "Immunohistochemical staining revealed that combination treatment with Salmonella and αPD-L1 significantly increased the infiltration of both CD4+ and CD8+ T cells into MC38 tumor site." (PMID 36605208, 2022). "We observed that infiltration of CD3+, CD4+, and CD8+ T cells was considerably lower in B16F10-R tumours than in B16F10-NR tumours." (PMID 36077671, 2022). "Tumor cell–specific depletion of SHP2 similarly reduced pulmonary metastasis and also relieved exhaustion markers on CD8+ and CD4+ cells." (PMID 36969745, 2022).
tumor (continued). "After treatment, large numbers of CD4+ T cells and MHC-II-positive macrophages infiltrated tumor tissue." (PMID 36159781, 2022). "Tregs suppress anti-tumor effector cells, including CD8+ T cells, CD4+ T cells, macrophages, NK cells, and neutrophils, through a variety of mechanisms." (PMID 36230810, 2022). "Before investigating the importance of the percentage of CD4+ T cells in CIK therapy, we need to understand the survival, tumor-killing ability, and movement of CIKs in vivo." (PMID 35523765, 2022). "Tumor immune microenvironment (TIME) is composed of tumor cells, fibroblasts, endothelial cells and immune cells, such as CD8+T cells, CD4+ T cells, T regulatory cells, neutrophils, macrophages, B cells, dendritic cells, and myeloid-derived suppressor cells." (PMID 35186039, 2022). "By the mechanism of self-adjuvanticity, ATP128 will allow DCs activation, antigenic presentation to tumor specific CD4 and CD8 T cells as observed with KISIMA surrogate treatment in tumor mouse models." (PMID 36291919, 2022). "A comparative analysis of the number of CD4+ and CD8+ lymphocytes in the tumor microenvironment in different studies showed mixed results." (PMID 36297616, 2022). "More importantly, in the rFlu-huCTLA4 group, we found that CD4+ and CD8 +T cells were significantly increased in tumor-bearing BALB/c mice." (PMID 35494032, 2022). "Various immune cells, such as CD8+ T cells, B cells, CD4+ T cells, neutrophils, and macrophages, secrete factors that influence the TIME, regulate tumor behavior, and have anticancer effects." (PMID 36052059, 2022). "These correlations suggested that MTUS1 can recruit immune T, Th1, Th2, Tcm, T helper, CD4+ T, and CD8+ T cells into the tumour microenvironment and prevent the recruitment of Treg cells that promote immune tolerance and angiogenesis." (PMID 35962436, 2022). "We observed a significant decrease in the C3 subtypes of multiple anti-tumor immune cells, including activated CD8 T cells, effector memory CD4 T cells, effector memory CD8 T cells, type 1 T helper cells, and type 17 T helper cells." (PMID 35252177, 2022). "DSP data from the tumor compartment were used for correlation analyses of ER, HER2, and Ki‐67, as these markers are predominantly expressed in the tumor, whereas DSP data from both the tumor and stromal compartments were evaluated for CD4 and CD8." (PMID 34018684, 2022). "While tumor development progressed in mice that received a sham treatment only, the combined action of the cytokines IFN-γ and TNF released by the transferred CD4+ Th1 cells led to senescence induction." (PMID 35326515, 2022). "One of the hallmarks of immune suppression is the paucity of tumor-infiltrating lymphocytes (TILs), characterized by low numbers of effector CD4+ and CD8+ T cells in the tumor microenvironment (TME)." (PMID 36159809, 2022). "Extranodal tumour involvement was initially identified in six of nine patients with CD8+ T-LPDs (67%), compared with one with CD4+ T-LPDs (9%) (p = 0.017)." (PMID 36544095, 2022). "The counts of effector T cells (e.g., CD4+ T cells and CD8+ T cells) were also decreased in tumor tissues of dysbiotic mice." (PMID 36726985, 2022). "The expression of WTAP was negatively correlated with tumor purity, but positively correlated with CD8 + T cells, CD4 + T cells, neutrophils, and dendritic cells." (PMID 35148766, 2022). "Of note, our study showed that enrichment of CD4+ T and B cells correlated with favorable clinical outcomes in NSCLC, and that IL-21 is critical for tumor control and B cells class switching to anti-tumor IgG1 and IgG3 isotypes." (PMID 35831283, 2022). "In line with the decreased Breg population upon MEK inhibition, numbers of tumor-infiltrating CD8+ and CD4+ T cells were found to be increased." (PMID 35965494, 2022). "Analysis through GENE module revealed that TIMP1 expression significantly correlates with tumor purity, the levels of B cells, CD8+ T cells, CD4+ T cells, macrophages, neutrophils, and dendritic cells." (PMID 35778451, 2022).